AGR2 (anterior gradient 2, protein disulphide isomerase family member)
Diseases named in the same sentence as AGR2 in open-access papers (continued):
Sharing a sentence is not in itself a finding about the gene and the disease.
pancreatic cancer (continued). "AGR2 has shown promise as a prognostic marker in prostate and pancreatic cancers, guiding immunotherapy strategies." (PMID 39062458, 2024). "In pancreatic cancer, AGR2 within cancer cells exerts a protective effect post-treatment with gemcitabine chemotherapeutic agents." (PMID 39062458, 2024). "Cancer-secreted AGR2 contributes to pancreatic cancer growth and metastasis by promoting endoplasmic reticulum retention and enhancing cancer cell viability." (PMID 39062458, 2024). "The mounting evidence underscores the importance of AGR2 in cancer immunotherapy, particularly in hepatobiliary and pancreatic cancers, suggesting its potential as a valuable target for novel therapeutic approaches." (PMID 39062458, 2024). "In pancreatic cancer, AGR2 expression is influenced by ERS, impacting pancreatic carcinogenesis, and AGR2 serves as a marker for cancer progenitor cells." (PMID 39062458, 2024). "Turning our attention to pancreatic cancer, clinical investigations have underscored the significance of AGR2." (PMID 39062458, 2024). "From the evidence presented in these studies, we can infer that AGR2 plays a role in the development and invasion of hepatobiliary and pancreatic cancers through both direct and indirect effects." (PMID 39062458, 2024). "In certain instances of pancreatic cancer, AGR2 shows promise as a potential tumor cell marker, particularly in ductal cells where it is significantly overexpressed in pancreatic tumors of ductal origin." (PMID 39062458, 2024). "Scholars have proposed AGR2 as a potential marker for ductal-origin pancreatic cancer due to this expression pattern disparity, potentially facilitating enhanced tumor classification for more effective cancer treatment." (PMID 39062458, 2024). "AGR2 shows potential as a marker for pancreatic cancer, particularly in the context of pancreatic ductal adenocarcinoma." (PMID 39062458, 2024). "Ongoing research investigating pancreatic cancer treatment strategies involving AGR2 shows promise for future therapeutic approaches." (PMID 39062458, 2024). "Various researchers have proposed that anti-AGR2 approaches have the potential for pancreatic cancer immunotherapy." (PMID 39062458, 2024). "AGR2, POSTN, TFF1, and CP were selected because their transcribed proteins have been previously implicated as potential biomarkers for pancreatic cancer." (PMID 36812168, 2023). "WH in pancreatic cancer cell lines PANC-1 with different forms of AGR2 revealed the enhanced activity of secreted AGR2 (AGR2 without the KTEL motif) in comparison with the cells with the wild-type AGR2 and control PANC-1 cells." (PMID 37175601, 2023). "The expression of AGR2 is also regulated by TGF-β, and its expression is associated with pancreatic cancer progression as well as with the progression of additional forms of cancer." (PMID 36232621, 2022). "In pancreatic carcinoma, AGR2 expression is related to the response to gemcitabine, and in an animal model, blocking monoclonal antibodies against AGR2 and C4.4A resulted in the regression of tumor invasion and increased survival." (PMID 36327302, 2022). "Previous studies show that intracellular AGR2 is predominantly localized in the ER of pancreatic cancer cells and is induced by ER stress." (PMID 33413231, 2021). "It has been demonstrated that AGR2 levels are elevated in a majority of pancreatic cancer cell lines, pancreatic intraepithelial neoplastic lesions, and pancreatic cancer lesions." (PMID 33413231, 2021). "In a proteomic analysis, cathepsin D and its family member cathepsin B were identified as interacting partners of the anterior gradient 2 (AGR2) protein in pancreatic cancer cells and involved cell dissemination." (PMID 34439122, 2021). "Stably silencing of AGR2 in MPanc-96 pancreatic cancer cells in which AGR2 is present in both cell lysates and conditioned media reduces cell proliferation and invasion." (PMID 33413231, 2021).
pancreatic cancer (continued). "Particularly in the context of pancreatic cancer, AGR2 was reported to be expressed and secreted during the progression of pancreatic cancer to promote the survival of cancer cells." (PMID 32322663, 2020). "In pancreatic cancer, the invasive potential of pancreatic cancer cells in vitro was proportional to the AGR2 expression level." (PMID 32024004, 2020). "We conclude that H-1-2 suppresses pancreatic cancer by inhibiting hypoxia-induced AGR2 expression, supporting further investigation into its efficacy against pancreatic cancer in clinical settings." (PMID 32322663, 2020). "Ectopic AGR2 expression partially negated the H-1-2 inhibitory effect on invasion and migration of pancreatic cells and on xenograft pancreatic tumors growth, and it also compromised the H-1-2 promotional effect on survival of mice." (PMID 32322663, 2020). "H-1-2 inhibits hypoxia, which consequently downregulates AGR2 expression, to suppress pancreatic tumor." (PMID 32322663, 2020). "In line with this, our current study is the first instance to provide evidence demonstrating the direct involvement of hypoxia-regulated AGR2 in tumorigenesis of human pancreatic cancer." (PMID 32322663, 2020). "H-1-2 repressed AGR2 expression in pancreatic cancer cells through the hypoxia response element (HRE) in its promoter region." (PMID 32322663, 2020). "Our results, where H-1-2 repressed AGR2 expression in pancreatic cancer cells through its anti-hypoxic function, provide yet another instance implicating AGR2 as an important prognosis factor for treatment against pancreatic cancer." (PMID 32322663, 2020). "We found that the polysaccharide H-1-2 suppresses pancreatic cancer by inhibiting hypoxia-induced AGR2 expression, supporting further investigation into its efficacy against pancreatic cancer in clinical settings." (PMID 32322663, 2020). "Deletion of the ER-retention motif enhanced the secretion of AGR2 and injecting this purified AGR2 mutant into the prostate and pancreatic cancer xenograft models increased the metastatic capabilities as compared to wild-type AGR2." (PMID 33005802, 2020). "We have previously demonstrated the expression and role of AGR2 in initiation of pancreatic cancer, and that premalignant lesions of both the prostate and pancreas show AGR2 expression." (PMID 31303962, 2019). "In another study, 109 out of 148 samples (74%) from pancreatic cancer patients had highly expressed AGR2 protein, with an elevated expression in female patients, and 139 out of 195 PDAC tissue samples (72%) had a high expression of AGR2." (PMID 31247903, 2019). "We have previously demonstrated the surface expression of AGR2 on human breast and pancreatic cancer cells." (PMID 31303962, 2019). "Biodistribution experiments using a syngeneic mouse model showed high uptake of P3A5 AGR2 antibody in xenografted eAgr2+ pancreatic tumors, with limited uptake in normal tissues." (PMID 31303962, 2019). "In pancreatic ductal adenocarcinomas (PDAC), AGR2 mRNA was found to be in mean 14-fold higher expressed in 56 out of 57 pancreatic cancer tissues (98%) than in normal and pancreatitis tissues." (PMID 31247903, 2019). "The important role of Smad4 in triggering AGR2 downregulation in human pancreatic cancer cells exposed to TGF-β has recently been shown." (PMID 28810836, 2017). "Oncogenic AGR2 was identified as the most significantly downregulated protein in miR-1291-expressing PANC-1 cells with lower capacity in proliferation and tumorigenesis, consistent with previous findings on the critical role of AGR2 in pancreatic cancer." (PMID 27322206, 2016). "Consistent with previous studies, our findings support the notion that AGR2 represents a druggable oncotarget for the development of new therapies to treat notoriously lethal pancreatic cancer." (PMID 27322206, 2016). "Our results demonstrated that miR-1291 was significantly downregulated in pancreatic cancer specimens, which was in contrast to the overexpression of oncogenic AGR2." (PMID 27322206, 2016).
pancreatic cancer (continued). "This is consistent with the observation that conditioned media from cells silenced for AGR2 have a reduced ability to stimulate proliferation of pancreatic cancer cells." (PMID 27240165, 2016). "AGR2 is secreted by pancreatic cancer cells, and localized on the cell surface of pancreatic cancer cells." (PMID 26894971, 2016). "The overexpression of AGR2 and downregulation of miR-1291 in pancreatic carcinoma indicates an inverse relationship between miR-1291 and AGR2 in pancreatic cancer." (PMID 27322206, 2016). "As further evidence of an extracellular role for AGR2, a recent study showed that the addition of extracellular recombinant AGR2 to pancreatic cancer cells promoted their growth, migration and invasion by signalling through the C4.4a cell surface receptor." (PMID 26169982, 2015). "Knockdown of AGR2 expression in MPanc-96 pancreatic cancer cell line and in SEG-1 esophageal adenocarcinoma cell line results in significant reduction of in vivo tumor growth." (PMID 25367337, 2014). "Whereas knockdown of AGR2 in pancreatic cancer cells decreases cell proliferation and invasion, and increases drug sensitivity, AGR2 expression in tissue samples of pancreatic cancer patients is positively correlated with differentiation status of the cancer." (PMID 25367337, 2014). "Such discrepancy between in vitro tumor-promoting role of AGR2 and tumor progression in patients has also been reported in pancreatic cancer studies." (PMID 25367337, 2014). "Silencing of AGR2 expression in MPanc-96 pancreatic cancer cell line significantly decreases tumor growth in a xenogeneic tumor model." (PMID 25367337, 2014). "In pancreatic cancer cells, AGR2 has been shown to be involved in invasion and dissemination through posttranscriptional regulation of cathepsins D and B." (PMID 24007603, 2013). "AGR2 levels in the pancreatic juice samples were found significantly elevated in patients with pre-malignant conditions (PanINs and IPMNs) as well as pancreatic cancer compared to control samples (p ≤ 0.03)." (PMID 20550709, 2010). "The pancreatic juice AGR2 level was significantly elevated in patients with premalignant lesions and pancreatic cancer compared to control samples." (PMID 20550709, 2010). "Previous reports have shown that knocking down AGR2 has an impact on growth in esophageal and pancreatic cancer cell lines." (PMID 20525379, 2010). "Along with these previous studies, it is evidenced that AGR2 is likely to be secreted into the pancreatic duct fluid early in pancreatic cancer progression." (PMID 20550709, 2010). "In this study, we found that AGR2 was significantly elevated in the pancreatic juice from patients with pre-malignant conditions (PanINs and IPMNs) as well as pancreatic cancer compared to control pancreatic juice samples." (PMID 20550709, 2010). "The level of pancreatic juice AGR2 was also significantly higher in pancreatic cancer compared to controls (p = 0.03)." (PMID 20550709, 2010). "This, together with our results, prompted us to further investigated AGR2 for its utility as a biomarker for pancreatic cancer." (PMID 20550709, 2010). "A recent study showed that AGR2 was highly expressed in the tissue of both PanIN lesions and pancreatic cancer." (PMID 20550709, 2010). "By ELISA, AGR2 levels in the pancreatic juice samples from patients with benign pancreatic disease, premalignant pancreatic neoplasia and pancreatic cancer were tested and compared." (PMID 20550709, 2010). "The same study also demonstrated that AGR2 was secreted into culture media by pancreatic cancer cells." (PMID 20550709, 2010). "ROC analysis was applied to evaluate the sensitivity and specificity of AGR2 in distinguishing premalignant and pancreatic cancer juice samples from benign controls." (PMID 20550709, 2010). "Previous study had reported high expression of AGR2 in neoplastic cells with 98% (56 of 57) positivity on pancreatic cancer and minimal staining in normal and pancreatitis tissues." (PMID 20550709, 2010).
pancreatic cancer (continued). "In the course of this investigation, the converse, siRNA- or shRNA-mediated AGR2 knockdown, was shown to inhibit colony and subcutaneous growth in esophageal and pancreatic cancer models." (PMID 20525379, 2010). "At 90% specificity, AGR2 had a sensitivity of 25% in discriminating pancreatic cancer juice samples from the control group." (PMID 20550709, 2010). "A recent study using IHC showed that AGR2 was highly expressed in both PanINs and pancreatic cancer tissues and is secreted into the culture media of pancreatic cancer cell lines." (PMID 20550709, 2010). "Further analysis of sequencing data of the pancreas of KC verse KC;Agr2−/− mice (PRJEB40643) proved that ferroptosis might be involved in the pancreatic cancer progression." (PMID 41326375, 2025). "Notably, human pancreatic cancer cells exhibit dose-dependent AGR2 upregulation upon exposure to ferroptosis inducers." (PMID 41326375, 2025). "Additionally, combining AGR2 antibodies with gemcitabine in mouse-transplanted human pancreatic cancers has demonstrated strong immunotherapeutic capabilities, exceeding gemcitabine treatment alone." (PMID 39062458, 2024). "In pancreatic cancer, AGR2 functions as a novel surface antigen that facilitates cancer invasion." (PMID 39062458, 2024). "Therefore, understanding the expression patterns of AGR2 in hepatobiliary and pancreatic cancers carries significant implications for exploring new avenues in cancer immunotherapy." (PMID 39062458, 2024). "The use of eugenic acid in pancreatic cancer reduced AGR2 expression in cancer cells." (PMID 39062458, 2024). "Elevated AGR2 expression levels were shown in seven of nine pancreatic cancer cell lines." (PMID 37175601, 2023). "However, the functional roles of extracellular and intracellular AGR2 in pancreatic cancer cells remain to be elucidated." (PMID 33413231, 2021). "In pancreatic cancer cells, AGR2 up-regulates the downstream effectors (e.g. cathepsin B and D) without changing their mRNA levels supporting that AGR2 could exert its effects on client proteins post-transcriptionally." (PMID 33717413, 2021). "Moreover, EGFR expression and activation were determined to explore the possible mechanism of AGR2 roles in pancreatic cancer tumorigenesis." (PMID 33413231, 2021). "Furthermore, AGR2 has been detected in conditional media culturing several pancreatic cancer cell lines, indicating that it is secreted." (PMID 33413231, 2021). "However, the contribution of different localizations of AGR2 to pancreatic cancer has yet to be elucidated." (PMID 33413231, 2021). "Overexpression of AGR2 has been reported in multiple solid human tumors, including breast, prostate, ovarian, lung, esophageal, gastric, colorectal and pancreatic cancers, suggesting it could be a unique biomarker in these tumors." (PMID 33413231, 2021). "Importantly, a recent study reported that overexpression of extracellular AGR2 in MiaPaCa-2 pancreatic cancer cells promotes tumor metastasis in vivo models." (PMID 33413231, 2021). "al. reported a murine blocking antibody against AGR2 that can reduce growth and metastasis of pancreatic cancers and suppress AGR2 client protein C4.4a, hence there are possibilities to use therapeutic agents to abrogate extracellular metastatic receptor activities." (PMID 33005802, 2020). "Moreover, in the mouse model, ectopic AGR2 expression also negated the H-1-2 inhibitory effect on growth of xenograft pancreatic tumors and the H-1-2 promotional effect on survival of mice." (PMID 32322663, 2020). "In pancreatic cancer cell models, AGR2 expression is upregulated upon tunicamycin treatment whereby AGR2 silencing resulted in the overexpression of ER stress marker XBP1s, suggesting a functional role of AGR2 in ER proteostasis." (PMID 33005802, 2020).
pancreatic cancer (continued). "Furthermore, as an ER stress protein, AGR2 reportedly preceded and contributed to the initiation of pancreatic cancer." (PMID 32322663, 2020). "We therefore reasoned that elevated HIF1α in pancreatic tumor tissues could lead to upregulated AGR2 expression as well, which was indeed confirmed by higher AGR2 mRNA levels in pancreatic tumor tissues than adjacent normal tissues." (PMID 32322663, 2020). "However, no prior investigation has been conducted on the role of hypoxia/AGR2 regulation in pancreatic cancer." (PMID 32322663, 2020). "In pancreatic cancer cells, for instance, AGR2 could escape the ER-retrieval machinery and localize on the surface of the plasma membrane." (PMID 33005802, 2020). "The fortuitous cross-reactivity between human AGR2 and mouse Agr2 suggests that a similar result could be obtained in pancreatic cancer patients with minimal targeting of iAGR2-expressing healthy cells." (PMID 31303962, 2019). "miR-1291 was shown to regulate expression of AGR2 in pancreatic cancer cell." (PMID 30665445, 2019). "The silencing of AGR2 in the MPanc-96 pancreatic cancer cell line using siRNA and shRNA significantly increased the effectiveness of gemcitabine treatments in 98% of neoplastic cells in comparison with cells that had a high AGR2 expression level." (PMID 31247903, 2019). "AGR2 has been shown to be up regulated in breast, prostate and pancreatic cancers." (PMID 28736504, 2017). "In vitro, AGR2 expression was stimulated by tunicamycin-induced endoplasmic reticulum (ER) stress in both KRAS wild-type normal pancreas cells, as well as in KRAS mutated pancreatic cancer cells and was essential for ER homoeostasis." (PMID 27941872, 2017). "Indeed AGR2 is overexpressed throughout the progression to pancreatic cancer and has been shown to facilitate the initiation, progression, and dissemination of pancreatic cancer." (PMID 27322206, 2016). "Our efforts were thus directed to understand how miR-1291 might regulate AGR2 expression in pancreatic cancer cells." (PMID 27322206, 2016). "AGR2 was highly overexpressed in our previous integrated proteomic analysis of cell lines and pancreatic juice as well, and our preliminary verification studies showed it to be significantly elevated in plasma from pancreatic cancer patients." (PMID 24007603, 2013). "Moreover, when we compared sera from pancreatic cancer cases and cancer-free controls, only 1/9 pancreatic cancer sera showed a high level of AGR2, compared to 0/9 cancer-free controls." (PMID 20550709, 2010). "We compared the AGR2 levels in samples (juice and serum) from controls (including benign diseases and chronic pancreatitis), patients with pre-malignant lesions (PanIN2, PanIN3 and IMPNs), and patients with pancreatic cancer." (PMID 20550709, 2010). "Thus, we hypothesize that AGR2 might regulate pancreatic cancer progression by regulating ferroptosis." (PMID 41326375, 2025). "Furthermore, AGR2 emerges as a potential cancer prognostic marker and a promising target for immunotherapy, offering novel avenues for the treatment of hepatobiliary and pancreatic cancers and enhancing patient outcomes." (PMID 39062458, 2024). "The protein products from AGR2, CEAMAN6, GNMT, PDIA2, POSTN, RBPJL and S100P have been reported as potential diagnostic and prognostic biomarkers for pancreatic cancer or have demonstrated to be involved in either pancreatic cancer, initiation, migration, invasion, metastasis, or chemoresistance." (PMID 36812168, 2023). "Indeed, our results indicated that H-1-2 could inhibit AGR2 and HIF1α expression in pancreatic cancer both in vitro and in vivo." (PMID 32322663, 2020). "A sharp reduction of AGR2 (current study) and significant change of cell metabolome are unified for miR-1291-expression PANC-1 cells, suggesting that miR-1291 may be implicated in the metabolism of pancreatic cancer cells." (PMID 27322206, 2016).